INS (insulin)
Diseases named in the same sentence as INS in open-access papers (continued):
Sharing a sentence is not in itself a finding about the gene and the disease.
type 2 diabetes (continued). "Invariably preceding the development of overt type 2 diabetes, there is a decrease in systemic insulin sensitivity referred to as insulin resistance, which is also a feature of chronic inflammatory conditions in non-diabetics." (PMID 23056469, 2012). "Other large-scale, long-term trials in type 2 diabetes can provide further information on the effect of insulin therapy on cancer incidence and cancer-related mortality." (PMID 23209929, 2012). "Chickens mimic the early stage of type 2 diabetes in humans, exhibiting both hyperglycemia (up to 200 mg/dL in the fasting state) and resistance to exogenous insulin." (PMID 22938590, 2012). "High levels of insulin administration are a concern however, as women who require insulin to control their GDM are considered to be at higher risk of developing type 2 diabetes in the future." (PMID 22988897, 2012). "While patients with Type 1 diabetes must take insulin to survive, many patients with Type 2 diabetes also require insulin supplementation in order to control persistent hyperglycaemia." (PMID 22313123, 2012). "The beneficial effects of RAS blockade in the prevention of type 2 diabetes have been explained by improved insulin sensitivity and insulin secretion." (PMID 22768174, 2012). "The cAMP signaling system contains important targets for pharmacological improvement of insulin secretion in type 2 diabetes." (PMID 22970724, 2012). "Respondents had been using insulin for an average of almost 9 years (Type 1 diabetes ∼15 years, Type 2 ∼8 years) and the majority used an insulin pen all or part of the time (Type 1 diabetes ∼76%, Type 2 diabetes ∼78%)." (PMID 22313123, 2012). "β-cell failure has been attributed to autoimmune assault in type 1 diabetes and to glucolipotoxicity, amyloid deposition, insulin resistance, and endoplasmic reticulum (ER) and/or oxidative stress in type 2 diabetes." (PMID 22470529, 2012). "Decreased DHEA levels in obese patients or those with type 2 diabetes are related to insulin-induced inhibition of enzyme activity for adrenal androgen synthesis." (PMID 22647230, 2012). "PPARγ ligands, like glitazones, are clinically used to treat type 2 diabetes as insulin-sensitizing drugs and PPARα ligands, like fibrates, are used to manage elevated blood lipid levels and type 2 diabetes as hypolipidemic agents." (PMID 23170129, 2012). "In conclusion, our current study demonstrated that aqueous extract of pepino improved insulin sensitivity and glycemic control, as well as attenuated cardiac oxidative stress in type 2 diabetic mice." (PMID 24527264, 2012). "So far, there is little information available on myocardial SERCA2a and PLB changes in the early stages of type 2 diabetes which is characterized by rather high insulin levels." (PMID 22621761, 2012). "Embryonic stem (ES) cell-derived insulin producing cells (IPCs) offer a potentially novel source of unlimited cells for transplantation to treat type 1 and possibly type 2 diabetes." (PMID 23369186, 2012). "It is easy to see how this can lead to a vicious cycle of progressive impairment of insulin secretion and elevation of plasma FFA levels until overt type-2 diabetes presents in genetically predisposed individuals." (PMID 22177710, 2012). "Patients with type 2 diabetes had higher HbA1c, fasting insulin, -C-peptide and -glucose compared to participants having NGT." (PMID 23251434, 2012). "For example, Islet amyloid polypeptide (IAPP) which is colocalized and secreted with insulin from β cell granules induces β cell apoptosis in cultured islets and in type 2 diabetes." (PMID 22474427, 2012). "It has a rapid stimulatory effect on insulin secretion and reduces postprandial plasma glucose level in patients with type 2 diabetes." (PMID 22748110, 2012).
type 2 diabetes (continued). "Supplementation with 200 to 1000 μg of chromium picolinate has been reported to improve glucose intolerance and lower circulating insulin levels with one study in type 2 diabetes patients showing a greater improvement with 1000 μg dose compared to 200 μg dose." (PMID 23194380, 2012). "In a community based national health survey, only 7.2% of Malaysian patients with type 2 diabetes used insulin, either alone or as combination therapy, compared to 36% in the United States." (PMID 22469132, 2012). "A total of 10189 patients with type 2 diabetes (mean age 61.18 ± 14.03 years; 52.2% male) were identified as receiving monotherapy of insulin, sulfonylureas, or metformin." (PMID 22719752, 2012). "Taken together, aerial parts of P. oleracea treatment markedly ameliorated hyperglycemia and impairment of insulin secretion and prevented diabetic endothelial dysfunction and vascular inflammation in type 2 diabetic db/db mice." (PMID 22474522, 2012). "Insulin injections became the standard treatment for type 1 diabetes and for many people with type 2 diabetes." (PMID 24278682, 2012). "The enzyme has been implicated in the pathogenesis of AD and type II diabetes due to its capabilities in degrading Aβ, AICD, amylin, insulin and insulin-like growth factors." (PMID 23210692, 2012). "Type 2 diabetes (T2D) is a heterogeneous and complex disease resulting from a combination of impaired pancreatic insulin secretion and insulin resistance in tissues such as skeletal muscle, adipose tissue, and liver." (PMID 23251491, 2012). "In later stages of type 2 diabetes, beta cells are unable to produce enough insulin, and then type 2 becomes more similar to type 1." (PMID 23612026, 2012). "To assess the proper insulin dosage and proper basal insulin to total daily insulin dose ratio in Chinese type 2 diabetic patients, we made this retrospective analysis in hospitalized patients receiving intensive insulin treatment by BBT." (PMID 22720003, 2012). "Network analysis revealed associations of these HE3286 target proteins with nodes in the Kyoto Encyclopedia of Genes and Genomes (KEGG) pathways for type 2 diabetes, insulin, adipokine, and adipocyte signaling." (PMID 22384159, 2012). "In the same study, one patient with type II diabetes actually reverted to a state in which glucose tolerance was impaired and insulin therapy ceased." (PMID 22234148, 2012). "Insulin levels are usually higher in early stages of Type 2 diabetes (or even in prediabetes) and decline consequently." (PMID 22262970, 2012). "Impaired mitochondrial oxidative capacity is also an early feature observed in insulin-resistant offspring of individuals with type 2 diabetes." (PMID 22203837, 2012). "Accordingly, it is well known that adiponectin insufficiency affects insulin sensitivity and in some cases has even been reported to be a prelude to type 2 diabetes." (PMID 23304216, 2012). "This alteration of insulin's effect, known as insulin resistance, is a major factor responsible for hyperglycemia in type 2 diabetes mellitus, and a prominent feature of metabolic syndrome." (PMID 22613805, 2012). "Treatment of type 2 diabetes (non-insulin dependent) is now possible with orally administered hypoglyceamic agents that help to reduce blood sugar levels." (PMID 23675267, 2012). "The aim of this study was to compare real-life daily doses of insulin detemir and insulin glargine in type 2 diabetes patients when administered once daily." (PMID 23009558, 2012). "Despite the availability of many other agents, insulin is widely used as a treatment for type 2 diabetes." (PMID 23209929, 2012). "One involves inapplicability of findings from western populations to the Japanese population due to potential ethnic differences in pathophysiology of type 2 diabetes: body anthropometry, insulin secretion capacity, contribution of insulin resistance, etc." (PMID 22870214, 2012).
type 2 diabetes (continued). "Nearly all patients were on pharmacological therapy for type 2 diabetes (94%): 244 were on oral hypoglycaemic therapy alone, 6 on subcutaneous insulin therapy alone and 25 on both." (PMID 21492425, 2011). "The in vivo deposition of insulin aggregates can lead to injection site problems for Type II diabetes patients, such as infection, bleeding, bruising, irritation, and inflammation." (PMID 22272138, 2011). "Basal insulin is widely recommended for patients with Type 2 diabetes who cannot achieve glycaemic goals with oral glucose-lowering medications alone." (PMID 21517955, 2011). "It was developed because of a lack of clinical knowledge at the time about the most appropriate ways to initiate insulin therapies in patients with type 2 diabetes, and how to help them achieve optimal blood glucose control on intensive insulin treatments." (PMID 21542916, 2011). "Cellular oxidative capacity, which mostly depends on mitochondrial function, is directly correlated with insulin sensitivity in skeletal muscles, and reduced mitochondria activity has been observed in patients with obesity and type 2 diabetes." (PMID 21464990, 2011). "This possibility was suggested by the finding that obese insulin resistant individuals and type 2 diabetics generally have about 30% less mitochondria in their skeletal muscles than age-matched individuals with normal insulin action." (PMID 21589859, 2011). "Resistance to insulin, resulting in decreased glucose uptake, is a major factor contributing to the development of type 2 diabetes." (PMID 21738773, 2011). "Like in human type 2 diabetes, the glucose intolerance in the GK rat is due partly to impaired insulin secretion, but also to reduced insulin sensitivity in target tissues." (PMID 21818330, 2011). "Similar, although non-significant, results were obtained in a study of Swedish type 2 diabetic patients treated with oral antihyperglycemic agents and/or insulin." (PMID 21777428, 2011). "Its large sample size and the inclusion of different specialists’ care provide a reliable representation of the Spanish patients with non-insulin-treated Type 2 diabetes." (PMID 21294772, 2011). "Type 2 diabetes is a chronic metabolic disorder characterized by hyperglycemia, variable degrees of insulin resistance, and impaired insulin secretion." (PMID 22046406, 2011). "Amyloid deposits of insulin have been observed both in patients with type II diabetes and in normal aging, as well as after subcutaneous insulin infusion and after repeated injection." (PMID 22132167, 2011). "Both insulin resistance and insulin secretory reserve are important in the pathogenesis of Type 2 diabetes, but to different extents in different people." (PMID 21480973, 2011). "The insulin-sensitizing properties of thiazolidinediones (TZDs), a family of PPARγ agonist compounds used to treat type 2 diabetes, have been traditionally attributed to their ability to enhance adipogenesis, via activation of PPARγ." (PMID 22087241, 2011). "The goal of type 2 diabetes treatment is to maintain a glycosylated hemoglobin (HbA1c) of < 7%, a goal that has been made easier through advances in insulin types and delivery options." (PMID 21226935, 2011). "Early stages of insulin aggregation, which involve the transient formation of oligomeric aggregates, are an important aspect in the progression of Type II diabetes and in the quality control of pharmaceutical insulin production." (PMID 22272138, 2011). "The purpose of this review is to summarize pharmacological studies of insulin analogues in patients with type 2 diabetes." (PMID 21410860, 2011). "This study examined the effect of postprandial vs. preprandial insulin glulisine on weight gain and glycaemic control in type 2 diabetes patients taking basal insulin." (PMID 21812890, 2011). "SNS activity is markedly increased in the insulin resistant state such as obesity and Type 2 diabetes." (PMID 21479217, 2011).
type 2 diabetes (continued). "High density lipoprotein (HDL) was reported to decrease plasma glucose and promote insulin secretion in type 2 diabetes patients." (PMID 21886796, 2011). "We believe the effect of shikonin on GLUT4 translocation is an important finding, because in the light of the increasing prevalence of type 2 diabetes it is vital to find and characterize insulin-independent pathways leading to glucose uptake." (PMID 21818330, 2011). "In a previous study we found that patients with type 2 diabetes had impaired insulin stimulated vasodilatation when treated with metoprolol compared to those treated with carvedilol." (PMID 21999413, 2011). "Considering that the regulation of glucose uptake into muscle cells via GLUT 4 is a fundamental action of insulin, and this process is impaired in type-2 diabetes, we examined the expression and translocation of GLUT 4 protein in soleus muscle." (PMID 19233878, 2011). "In the case of ‘adult-onset’ type 2 Diabetes, pancreatic islet β-cell function can be impaired such that insufficient insulin is produced, or cells become resistant to insulin." (PMID 21566262, 2011). "Plasma glucose and insulin levels were significantly higher for the HF group than for the LF group, and severe type II diabetes was induced." (PMID 21799697, 2011). "Among those with type 2 diabetes, three were on metformin alone, one was on glyburide alone, one was on a combination of metformin and glyburide, one was on insulin and three were diet controlled." (PMID 22164267, 2011). "Most patients with Type 2 diabetes are insulin resistant, and "paying lip service" to dietary and lifestyle therapies leads to overinsulinization." (PMID 21668983, 2011). "Since insulin signaling is impaired in type 2 diabetes it is of great interest to find molecules and mechanisms that regulates glucose uptake in peripheral tissues." (PMID 21818330, 2011). "As a result of these findings, health professionals have, until recently, been encouraged to adopt aggressive approaches to controlling blood glucose levels amongst their type 2 diabetes patients, including early initiation onto insulin." (PMID 21542916, 2011). "Impairment of insulin secretory capacity has been shown to contribute to the onset of type 2 diabetes." (PMID 21886784, 2011). "INCB013739 treatment of type 2 diabetes mellitus patients who failed on metformin monotherapy show significantly improved hepatic and peripheral insulin sensitivity and reduced haemoglobin A1c and fasting plasma glucose levels." (PMID 21714097, 2011). "We then investigated the effect of TNFRSF1B polymorphisms on quantitative metabolic traits related to type 2 diabetes viz BMI, WHR, HbA1c, fasting glucose, insulin, C-peptide, total cholesterol, TG, HDL-C, LDL-C, urea, uric acid and creatinine." (PMID 21849023, 2011). "Another group reported that EGb761 ingestion increased plasma insulin levels in response to oral glucose loading in subjects with type 2 diabetes." (PMID 21655098, 2011). "Patients with type 1 diabetes fail to produce insulin, and patients with type 2 diabetes develop resistance to insulin." (PMID 21912601, 2011). "The high-fat diet-fed C57BL/6J mouse is an ideal model for studying mechanisms of impaired glucose tolerance along with insulin resistance leading to type 2 diabetes marked by islet dysfunction and for developing novel therapeutic interventions." (PMID 21785636, 2011). "In particular, the impairment of insulin signalling by uncontrolled PTP1B activity has been correlated with the appearance of both type II diabetes and AD." (PMID 21294893, 2011). "In patients with type 2 diabetes, both insulin lispro and insulin aspart administered immediately before meals have showed an 18–48% reduction in the rise of the 2-h postprandial glucose relative to human insulin given 30 min before the meal." (PMID 21410860, 2011). "Type 2 diabetes is characterized by two basic abnormalities: impairment of insulin secretion and decrease in insulin action." (PMID 23554718, 2011).
type 2 diabetes (continued). "The aim of this study was to examine the effect of Ras inhibition on insulin sensitivity and glucose uptake, as well as its influence on type 2 diabetes development." (PMID 21738773, 2011). "The male patients had a significantly higher prevalence of hypertension, type 2 diabetes and ischemic heart disease, as well as higher levels of fasting insulin, glucose and HbA1c than the female patients." (PMID 21284837, 2011). "An enhanced beta-cell function, as evidenced by an increased insulin release in response to glucose stimulation, has been observed early in the pathogenesis of type 2 diabetes in animal models." (PMID 21244699, 2011). "Abnormalities of insulin clearance are present in various pathological conditions including type 2 diabetes and severe obesity." (PMID 21569294, 2011). "Type 2 diabetes is a common disease that is characterized by chronic hyperglycemia due to impaired insulin secretion and decreased insulin action." (PMID 23675229, 2011). "Two decades ago, cinnamon (Cinnamomum zeylanicum) was proposed as a treatment for type 2 diabetes (T2D) when it was shown to display insulin-mimetic properties." (PMID 21899741, 2011). "The aim of this study was to examine the antidiabetic effect of palmitoleic acid in KK-Ay mice, a spontaneous model for studies of obese type 2 diabetes with low insulin sensitivity." (PMID 21774832, 2011). "Suppressed pancreatic β cell insulin production and impaired glucose uptake in skeletal muscle, are major contributors to hyperglycemia, which eventually leads to Type II diabetes." (PMID 21701685, 2011). "It is therefore important to clarify the mechanism of the impairment of insulin secretory capacity in order to elucidate the mechanism of pathogenesis of type 2 diabetes." (PMID 21886784, 2011). "It has been reported that S. reticulata improved hemoglobin A1c in patients with type 2 diabetes and suppressed increases in blood glucose and blood insulin levels in clinical studies, and it is assumed that S. reticulata improves glucose metabolism." (PMID 19505975, 2011). "In spite of having comparable BMIs and waist circumferences, our results from HEC suggested that type 2 diabetes in AA is more insulin resistant compared with type 1 diabetes and healthy controls." (PMID 22164267, 2011). "Clauson and Linde reported 15–45% slower absorption kinetics of human insulin (Actrapid) in obese and normal body weight type 2 diabetes patients relative to previously studied patients with type 1 diabetes." (PMID 21410860, 2011). "Eventually, the pancreas fails to maintain insulin production in the face of steadily increasing insulin demand, leading to the development of type 2 diabetes." (PMID 22035457, 2011). "In rosiglitazone-treated obese patients with type 2 diabetes, improved insulin sensitivity and skeletal muscle oxidative enzyme activity is associated with an upregulation of PPARδ expression." (PMID 22190906, 2011). "The subsequent production of pro-inflammatory cytokines, including IL6 and TNFα, will interfere with insulin signalling leading to type 2 diabetes and further propagate the state of chronic inflammation." (PMID 21193034, 2011). "Consistent with decreased gene expression, insulin-resistant offspring of patients with type 2 diabetes exhibit diminished mitochondrial oxidative capacity." (PMID 22087241, 2011). "Type 2 diabetes (T2D), classically arises as a result of defects in insulin secretion and insulin action." (PMID 21673955, 2011). "Insulin secretion is often deteriorated in various degrees in Japanese and the other Asian patients with type 2 diabetes compared to Caucasian, and thus the effect of liragulutide on insulin secretion is worth evaluating in Japanese type 2 diabetes subjects." (PMID 22132774, 2011). "This review summarizes pharmacokinetic and pharmacodynamic studies of insulin analogues performed in patients with type 2 diabetes." (PMID 21410860, 2011).